FDFT1 (farnesyl-diphosphate farnesyltransferase 1)
Diseases named in the same sentence as FDFT1 in open-access papers (continued):
Sharing a sentence is not in itself a finding about the gene and the disease.
tumor (continued). "Furthermore, it seems that tumor tissues have low expression of ACSL3, FDFT1, and HMGCR, and the high expression of ACSL3, FDFT1, and HMGCR patients was shown to be significantly associated with better OS and DFS, which indicated the suppression roles in carcinogenesis." (PMID 35322581, 2022). "To date, there is no direct evidence showing an association between FDFT1 and immune evasion in tumours; however, it may contribute to suppression of immunity in the TME by mediating cholesterol biosynthesis." (PMID 33113804, 2020). "The MREs ACAT1, ACAT2, FDFT1, FDPS, HMGCL and PMVK were highly expressed in basal tumor cells and urothelial cells." (PMID 39521858, 2024). "By analyzing the clinical information of 101 RMS patients, we observed that the upregulation of MVP genes, especially HMGCR, farnesyl-diphosphate farnesyltransferase 1 (FDFT1), and SQLE, was correlated with the advanced tumor grade." (PMID 39706565, 2024). "The results showed that the expression of HAMP, FDFT1, GDF15, TFAP2C all increased in tumor tissues, indicating their meaningful regulatory roles in CRC." (PMID 34249766, 2021). "Cholesterol depletion by interfering with FDFT1 seems to induce CD44 shedding and delocalization of the focal adhesion complex from rafts, thereby suppressing tumour cell migration and invasion." (PMID 33113804, 2020). "In addition, high USP32 expression plays a crucial role in tumor growth, metastasis, immune infiltrates, and chemoresistance via the deubiquitination of various substrate proteins, such as Smad2, SHMT2, FDFT1, Rab7, SLC35F2, and BAG3." (PMID 40136417, 2025). "Fdft1 knockout shows no decrement in 2D tumor cell proliferation but exhibits growth inhibition in 3D culture and orthotopic transplanted tumor cells." (PMID 37958351, 2023). "A recent report has found that fasting could induce the upregulation of FDFT1, a tumor suppressor gene to attenuate the AKT/mTOR/HIF pathway, thus inhibiting tumor glycolysis and proliferation in a CRC mouse model." (PMID 36319992, 2022). "In the Th17 lineage, RORC (receptor) is upregulated on the tumor infiltrating CD4+ T-cells and its ligands (CYP51A1, FDFT1, HSD17B7, LBR, TM7SF2, MSMO1, NSDHL) are also upregulated on the tumor cells, implying GBM expresses ligands that induces Th17 phenotype in tumor infiltrating helper T-cell." (PMID 34012510, 2021). "Similarly, our data likewise found that the expression of FDFT1 in tumor cell lines was not entirely consistent." (PMID 40438588, 2025). "In addition, we constructed a DEN/CCL4‐ induced HCC mouse model and found that FDFT1 expression was obviously higher in tumor tissues than in nontumor tissues." (PMID 39899681, 2025). "Furthermore, NGS analysis revealed that NF-κB/RELA targets including CCL2, CXCL8, EDN1, IL-1β, IL-6, and SERPINE1 were further reduced and several potential tumor suppressors, such as FABP3, FADS2, FDFT1, SEMA6A, and PCK2, were synergistically induced by the Gefitinib-+IKK16 treatment." (PMID 36358633, 2022). "Moreover, FDFT1 could act downstream of neurotrophic factors IGF-1 and bFGF, which together are one of the three molecular groups involved in tumour-neural crosstalk." (PMID 33113804, 2020).
cancer (34 papers, 2017 to 2025). A tumor composed of atypical neoplastic, often pleomorphic cells that invade other tissues. "Gathering evidence has indicated that FDFT1 expression increases in cells undergoing proliferation, suggesting that FDFT1 is implicated in proliferative signaling in cancer cells." (PMID 37834468, 2023). "In various cancers, including ovarian cancer, FDFT1 is associated with invasion and activates cancer cell metastasis through MMP1, CD44, and AKT/mTOR/HIF1α signaling." (PMID 37107644, 2023). "Among the six key PRSGs, NRIP2 and FDFT1 correlate with many cancer-associated TFs and hallmarks of cancer gene sets in the regulatory network." (PMID 35794546, 2022). "FDFT1, a membrane-associated enzyme, is also crucial for cancer development, particularly in metabolic reprogramming." (PMID 35794546, 2022). "While increased gene expression of FDFT1 has been implicated in the development of certain types of cancers, the FDFT1gene locus has been observed as the site of deletions in other cancers." (PMID 33113804, 2020). "In prostate cancer, an association of the rs2645429 polymorphism of the FDFT1 gene with cancer progression and an invasive phenotype was observed." (PMID 33113804, 2020). "In prostate cancer, the association of the rs2645429 polymorphism of FDFT1 gene has also been observed with progression and invasive phenotypes of this cancer." (PMID 29765975, 2018). "Moreover, high levels of farnesyl-diphosphate farnesyltransferase 1 (FDFT1) have been implicated in the development of certain types of cancers." (PMID 35008958, 2022). "In cancer cells with deficient squalene epoxidase, high expression of FDFT1 increased intracellular squalene levels, which protects the cell membrane from lipid peroxidation by reactive oxygen species (ROS) and further prevents the cell from entering the ferroptosis pathway." (PMID 33113804, 2020). "However, none of these interacting molecules has been studied for their association with FDFT1 in reports focused on cancer metabolism." (PMID 33113804, 2020). "Beyond stem cells, down-regulating expression of FDFT1 markedly reduced endogenous cellular cholesterol content, with selective effects noted in raft-associated fractions, resulting in apoptotic sensitivity and cancer cell growth suppression." (PMID 33113804, 2020). "It has been proven that farnesyl-diphosphate farnesyltransferase 1 (FDFT1) participate in oncogenesis and development of cancers." (PMID 40438588, 2025). "The expression of FDFT1 is significantly elevated during cell proliferation, indicating its involvement in proliferative signaling in cancer cells." (PMID 40145543, 2025). "Abnormal expression of FDFT1 occurs in a wide variety of cancers, making it a potential candidate biomarker and a novel target for cancer therapy." (PMID 40145543, 2025). "FDFT1 is also among the top 1% of genes with copy number gain in multiple cancer cell lines that are sensitive to panobinostat." (PMID 35093030, 2022). "Due to the connection of cholesterol metabolism to cancer, FDFT1 has been considered as a cancer prognostic marker and a target for anticancer therapy." (PMID 35976950, 2022). "The model identified universal correlation between NRIP2 and FDFT1 (key PRSGs), and some cancer related transcription factors (TFs) and trademarks of cancer gene were in the regulatory network." (PMID 35794546, 2022). "The results showed that in the FDFT1 overexpression group, cell migration and invasion were hampered compared with the corresponding NC group, indicating the potential cancer suppression ability." (PMID 35322581, 2022). "The anti-cancer effect of ET combination is dependent on the presence of endogenous expression of FDFT1, while the FDFT1 is the key enzyme to produce squalene." (PMID 33986254, 2021). "Farnesyltransferase 1 (FDFT1), as a novel target in basic research, has been reported to regulate malignant progression in some types of cancer." (PMID 34953498, 2021).
cancer (continued). "Farnesyl-diphosphate farnesyltransferase 1, a key enzyme of cholesterol synthesis, increases lipid raft content in the membranes of cancer cells." (PMID 33450869, 2021). "GS is a classical approach to limiting cancer growth, which inhibits malignancy by regulating the miR-216a-5p/FDFT1 axis." (PMID 34953498, 2021). "In this study, we found that FDFT1 was overexpressed in GC and negatively correlated with some pathological characteristics, including pT stage, pTNM stage and cancer differentiation." (PMID 34953498, 2021). "We have summarized how FDFT1 is involved in the development of cancer by dividing it into the functional hallmarks of cancer originating from the cancer cells themselves or the TME." (PMID 33113804, 2020). "Among the proteins interacting with FDFT1, those related to cancer metabolism include EGFR, FN1, sodium-taurocholate co-transporting polypeptide (SLC10A1), and WWOX." (PMID 33113804, 2020). "Inhibiting FDFT1 with zaragozic acid A also attenuated proliferation and induced the cell death of cancer cells." (PMID 33113804, 2020). "In the future, we anticipate that FDFT1 inhibitors will be used as a new weapon to overcome refractory cancer by overcoming some of these problems." (PMID 33113804, 2020). "Although attempts were made to understand the role of FDFT1 through its interacting proteins, few studies have been reported on how most interacting molecules participate in FDFT1-involved hallmarks of cancer." (PMID 33113804, 2020). "This review focuses on the contribution of FDFT1 to the hallmarks of cancer, and further, we discuss the applicability of FDFT1 as a cancer prognostic marker and target for anticancer therapy." (PMID 33113804, 2020). "FDFT1 has become a potential target in cancer due to its expression as a biomarker for the diagnosis of various cancers." (PMID 33113804, 2020). "The significance of the genetic diversity of the FDFT1 gene in diseases such as cancer and hepatitis C has been partially studied." (PMID 33113804, 2020). "FDFT1 is significantly upregulated in high metastatic potential cancer cell lines and higher-grade cancer." (PMID 33113804, 2020). "FDFT1 has frequently been found to be upregulated in cancers and to have significant effects on metabolic processes in cancers." (PMID 33113804, 2020). "Accumulating evidence has noted that FDFT1 plays a critical role in cancer, particularly in metabolic reprogramming, cell proliferation, and invasion." (PMID 33113804, 2020). "Based on the evidence, FDFT1 is likely to be involved in cancer growth and progression through regulatory interactions involving the nervous system." (PMID 33113804, 2020). "Given the mentioned points and the importance of the mevalonate pathway in the onset and development of cancer, the present study was designed to determine the relationship between NSCLC and FDFT1 rs2645429 polymorphism gene for the first time." (PMID 29765975, 2018). "FDFT1 is highly expressed in sphere‐forming stem cells of BC and neuroblastoma, which demonstrate a substantial capacity for both self‐renewal and differentiation, as well as resistance to cancer therapies." (PMID 40145543, 2025). "The abnormal expression of FDFT1 occurs in various cancers, which might be a novel candidate biomarker and a putative new target for cancer therapy." (PMID 37834468, 2023). "In addition, FDFT1 is one of the key enzymes for the synthesis of cholesterol; therefore, the study of FDFT1 in cancer development is of great importance in cancer management." (PMID 35322581, 2022). "In addition, accumulated evidence has revealed that FDFT1 has a key effect on carcinoma, especially in metabolic reprogramming, cell proliferation, and invasion." (PMID 36160009, 2022).
cancer (continued). "Reports to date suggest oncogenic effects of FDFT1, such as promoting proliferation, increasing anti-apoptotic protein levels, and preventing ferroptosis by increasing squalene levels in some cancer types, and conversely, plays an anti-oncogenic role in other cancers." (PMID 34820325, 2021). "The role of FDFT1 in cancer development is ambiguous at present." (PMID 34820325, 2021). "There are numerous reports on the role of FDFT1 affecting the hallmarks of cancer." (PMID 33113804, 2020). "FDFT1 via cholesterol, plays an essential role in the formation and growth of cancer stem cells." (PMID 33113804, 2020). "The SNP rs2645429 genotype of the FDFT1 gene was examined in patients with NSCLC, showing that the C allele may be a risk factor for this cancer." (PMID 33113804, 2020). "Gathering evidence has shown that FDFT1 expression increases in cells undergoing proliferation, suggesting FDFT1 in significant ways, contributes to the maintenance of proliferative signalling in cancer cells via several mechanisms." (PMID 33113804, 2020). "Based on these lines of evidence, inhibitors of FDFT1 may be promising adjuvants of the antitumour immune responses and should be combined with immunotherapy to treat cancer patients." (PMID 33113804, 2020). "Moreover, we would like to present the potential of FDFT1 as both a therapeutic target and a biomarker in cancer, and highlight recent trends in the development of FDFT1 inhibitors." (PMID 33113804, 2020). "However, in this review, we have only focused on FDFT1 inhibitors that demonstrated their effectiveness in cancer treatment." (PMID 33113804, 2020). "Among them, farnesyl-diphosphate farnesyltransferase 1 (FDFT1, EC 2.5.1.21, squalene synthase) has been regarded as a likely target in cancer due to its high expression as a biomarker used for diagnosis of various cancers, although in some cancers FDFT1 exhibits lower expression." (PMID 33113804, 2020). "Despite this, many novel inhibitors of FDFT1 have proven effectiveness in reducing cholesterol synthesis and may offer future potential in cancer treatment." (PMID 33113804, 2020). "FDFT1 is highly expressed in mammospheres, and neuroblastoma sphere-forming cells, which are cancer stem cells that exhibit self-renewal and differentiation capabilities as well as cancer therapy-resistant characteristics." (PMID 33113804, 2020). "This difference may be due not only to changes in FDFT1 expression but also to differences in how various cholesterol metabolites in cancers result in different responses." (PMID 33113804, 2020). "The genetic diversity of FDFT1 gene has been studied in a number of diseases, including cancers." (PMID 29765975, 2018). "Therefore, there may be limitations in developing FDFT1 as a cancer therapeutic target, mainly attributed to its heterogeneity in tumors." (PMID 40438588, 2025). "We then explored whether miR-216a-5p/FDFT1 axis regulates glycolysis of cancer." (PMID 34953498, 2021). "Although interactions between FDFT1 and its partners have been determined by the different methods such as affinity capture-MS and yeast two-hybrid, most of these interacting molecules have been not studied for their association with FDFT1 in reports focused on the hallmarks of cancer." (PMID 33113804, 2020). "Based on these advances in our knowledge, FDFT1 could be a potential target for cancer treatment." (PMID 33113804, 2020). "Therefore, whether FDFT1 can regulate genomic instability through partnerships with these interactions and how it affects cancer may be worthy of further study." (PMID 33113804, 2020). "The mRNA levels of CDKN1A, EMC2, FDFT1, HSPB, and MT1G, were analyzed comprehensively, and any correlations between the levels of mRNA of these five genes and pan-cancer prognosis were identified." (PMID 40432442, 2025). "CDKN1A, EMC2, FDFT1, HSPB1, and MT1G were assessed for their ability to serve as prognostic indicators in pan-cancer by utilizing the TCGA database." (PMID 40432442, 2025).
cancer (continued). "The expression of mRNA of CDKN1A, EMC2, FDFT1, HSPB1, and MT1G in the TCGA and GTEx datasets were evaluated through the analysis of pan-cancer." (PMID 40432442, 2025). "FDFT1 was downregulated in GC and negatively correlated with pathological T stage, pathological TNM stage and cancer differentiation." (PMID 34953498, 2021). "Specifically, we analyzed the role of five lncRNAs (BBC3, STK11IP, XIST, FDFT1, and PRR14), which are known to be related to cell growth and apoptosis in cancer development." (PMID 34295808, 2021). "The interaction between FDFT1 and CD74-CD44 could also facilitate cell migration, as CD74-CD44 combination increases phosphorylation of the actin severing protein cofilin to promote actin polymerization and F-actin formation, causing more efficient migration and invasion of cancer cells." (PMID 33113804, 2020). "In addition, PGRMC1 was shown to interact with FDFT1, SCD1 (SCD5 homologue) and is overexpressed in hormone receptor-positive breast cancer that correlated with enhanced cancer cell proliferation and lipid raft formation." (PMID 34440098, 2021). "However, the oncological functions of FDFT1 remained controversial in some types of cancer and the role of FDFT1 in GC has not been reported." (PMID 34953498, 2021).
immune disease (1 paper, 2025). "While more research is needed, our data suggest that FDFT1 is a novel immunomodulator, and validates the power of 3D chromatin-based autoimmune variant-to-gene mapping strategies for identifying therapeutic targets for immune disease." (PMID 41361473, 2025).
FDFT1 also shares sentences with these, for which no sentence is quoted: infection (4 papers); diabetes (2); fungal infections (2); gastric cancer (2); Hypercholesterolemia (2); multiple sclerosis (2); myopathy (2); amyotrophic lateral sclerosis (1); bacterial infections (1); Chagas disease (1); endometritis (1); epilepsy (1); heart disease (1); heart failure (1); Huntington disease (1); Insulin resistance (1); kidney tumors (1); leishmaniasis (1); liposarcoma (1); Listeria infection (1); liver cancer (1); lung adenocarcinoma (1); metabolic disease (1); metastatic tumors (1); mevalonate kinase deficiency (1); morbid obesity (1); neuropathy (1); nonalcoholic steatohepatitis (1); systemic lupus erythematosus (1); thyroid cancer (1).
A further 2 diseases each share a sentence with FDFT1 in 1 paper.